PHF2 (PHD finger protein 2)
Diseases named in the same sentence as PHF2 in open-access papers (continued):
Sharing a sentence is not in itself a finding about the gene and the disease.
leukemia (1 paper, 2024). A malignant (clonal) hematologic disorder, involving hematopoietic stem cells and characterized by the presence of primitive or atypical myeloid or lymphoid cells in the bone marrow and the blood. "Thus, PHF2 acts as a crucial tumor-inhibiting factor, with its downregulation associated with the aggressive behavior of leukemia cells." (PMID 38813086, 2024). "Specifically, PHF2’s reduction correlates with enhanced leukemia proliferation and poor prognosis in B-cell ALL, acting through IKAROS enhancement." (PMID 38813086, 2024). "PHF2 acts as a histone demethylase, reducing leukemia cell proliferation by influencing histone marks and tumor suppressor gene transcription." (PMID 38813086, 2024). "PHF2 expression is markedly diminished in ALL patients, correlating with increased leukemia cell proliferation and adverse prognostic markers in B-cell ALL." (PMID 38813086, 2024).
liver cancer (1 paper, 2023). An epithelial or non-epithelial malignant neoplasm that arises from the liver. "HepG2 and Hep3B cells were treated with various FAs, of which PA reduced PHF2 levels; PA also reduced PHF2 expression in other liver cancer cell lines." (PMID 37828054, 2023).
liver fibrosis (1 paper, 2018). "As a result, Phf2 silencing enhanced liver fibrosis development when compared to USi mice upon HFHSD feeding." (PMID 29844386, 2018).
lung adenocarcinoma (1 paper, 2023). A carcinoma that arises from the lung and is characterized by the presence of malignant glandular epithelial cells. "Analyses of data in TCGA revealed that PHF2 was significantly downregulated in lung adenocarcinoma (LUAD) and Lung squamous cell carcinoma (LUSC)." (PMID 36872368, 2023).
lung carcinoma (1 paper, 2023). "Consistently, the lung metastasis nodules displayed increased number in the PHF2 knockout group after sacrificed, indicating that PHF2 deficiency enhanced lung cancer metastasis in vivo." (PMID 36872368, 2023). "And PHF2 deficiency abolished the downregulation of H3K9me2 and inhibition of lung cancer metastasis of metformin." (PMID 36872368, 2023). "Metformin treatment significantly attenuated lung cancer metastasis of scramble group, while PHF2 deficiency abolished the anti-metastasis effect of metformin." (PMID 36872368, 2023). "We applied functional rescuing experiments in PHF2 knock-out cells and found that CDH1 almost rescued the enhanced lung cancer cell migration and invasion caused by PHF2 deficiency." (PMID 36872368, 2023). "And whether α-KG metabolites regulating lung cancer metastasis associated with PHF2 also worth subsequent research." (PMID 36872368, 2023). "We found that H249A mutant dampened the ability of PHF2 to inhibit lung cancer cell migration, invasion and EMT, indicating the demethylase activity of PHF2 is essential for its anti-metastasis function." (PMID 36872368, 2023). "Correspondingly, reintroduction of PHF2-WT, instead of S655A mutant, significantly suppressed lung cancer cell migration and invasion." (PMID 36872368, 2023). "To conclude, these results support a crucial role of AMPK mediated PHF2 phosphorylation at S655 in suppressing lung cancer metastasis." (PMID 36872368, 2023). "Inspired by the in-vitro results, we further applied the orthotopic LLC transplantation model in vivo and found in the S655A group, metformin hardly suppressed lung cancer metastasis compared with PHF2-WT group." (PMID 36872368, 2023). "Altogether, we reveal the mechanism of AMPK inhibiting lung cancer metastasis via PHF2 mediated H3K9me2 demethylation, thereby promoting the clinical application of metformin and highlighting PHF2 as the potential epigenetic target in cancer metastasis." (PMID 36872368, 2023). "We found mice injected with PHF2-WT cells developed slower and fewer pulmonary metastasis than mock group, while S655A mutant abolished the function of suppressing lung cancer metastasis according to the bioluminescent (BLI) imaging." (PMID 36872368, 2023). "To explore the biological importance of S655 phosphorylation in lung cancer metastasis, we compared PHF2 expression and the phosphor S655 level between A549 of high mesenchymal characters and PC-9 cells with high epithelial properties." (PMID 36872368, 2023). "More importantly, high PHF2 expression correlated well with better overall survival and relapse-free survival of lung cancer patients, suggesting PHF2 is of high clinical significance in lung cancer." (PMID 36872368, 2023). "Genetic deletion of PHF2 aggravates lung cancer metastasis and abolishes the H3K9me2 downregulation and anti-metastasis effect of metformin." (PMID 36872368, 2023). "AMPK phosphorylates PHF2 at S655 to enhance its histone demethylase activity and trigger epigenetic reprogramming of epithelial genes, thus suppressing lung cancer metastasis." (PMID 36872368, 2023). "Accordingly, PHF2 inhibits lung cancer cell migration, invasion, and metastasis in vitro and in vivo." (PMID 36872368, 2023). "This study identifies PHF2 as an important downstream effector of AMPK that inhibits lung cancer metastasis, highlighting PHF2-S655 phosphorylation as the potential biomarker in lung cancer metastasis and promoting the clinical application of metformin into suppressing tumorigenesis and development." (PMID 36872368, 2023). "Furthermore, the PHF2-S655E mutant that mimics AMPK-mediated phosphorylation status further reduces H3K9me2 and suppresses lung cancer metastasis, while PHF2-S655A mutant presents opposite phenotype and reverses the anti-metastasis effect of metformin." (PMID 36872368, 2023).
lung carcinoma (continued). "Together, these findings demonstrate a mechanism of AMPK downregulating H3K9me2 modification and provide new insights of PHF2 as the potential epigenetic target in lung cancer metastasis, thereby promoting the clinical application of metformin into suppressing tumor development." (PMID 36872368, 2023). "Given PHF2 was reported as tumor suppressor in previous studies, we applied The Cancer Genome Atlas (TCGA) database to explore the correlation of PHF2 expression in lung cancer." (PMID 36872368, 2023). "Thus, before further demonstrating AMPK activation inhibits lung cancer metastasis via PHF2, we were required to confirm whether PHF2 presents the ability to inhibit lung cancer metastasis via demethylation activity." (PMID 36872368, 2023). "Therefore, PHF2 is essential for metformin inhibiting lung cancer metastasis." (PMID 36872368, 2023). "We generated PHF2 knockout A549 and H1299 cell lines (KO1 and KO2 cells) with CRISPR-Cas9 to evaluate its effect on lung cancer metastasis." (PMID 36872368, 2023).
malignant melanoma (1 paper, 2018). "Though PHF2 was less toxic to fibroblast cells, it exhibited low anti-oxidant capacity, anti-elastase capacity and was also less cytotoxic to malignant melanoma cells." (PMID 29378653, 2018). "When tested against human malignant melanoma A375 cell line, PHF1 exhibited higher inhibitory activity (61.88%) with an IC50 value of 199.13 μg/mL, than PHF2." (PMID 29378653, 2018).
metastatic disease (1 paper, 2020). "Similar to our findings in the orthotopic model, stable depletion of KDM5A and PHF2 each resulted in a robust decrease in metastatic disease burden in this model." (PMID 33196691, 2020). "Similarly, depletion of PHF2 resulted in a reduction in overall disease burden and primary tumor size, and a more pronounced decrease in metastatic disease burden (bottom)." (PMID 33196691, 2020).
non-alcoholic fatty liver disease (1 paper, 2024). "Phf2 physiologically regulates adipogenesis, chondrogenesis, non-alcoholic fatty liver disease (NAFLD) progression, and memory formation, while its role in skeletal muscles remains unclear." (PMID 38701072, 2024).
tumor (21 papers, 2008 to 2025). "PHF2 is a positive epigenetic modulator and is linked to tumor suppression in various kinds of cancer." (PMID 32085659, 2020). "PHF2 encodes a histone demethylase with tumor suppressor activity." (PMID 32051441, 2020). "We also tested whether PHF2 loss could increase the tumor growth of HCC cells." (PMID 37828054, 2023). "Here, we found that PHF2 is an intrinsic tumor suppressor as a ubiquitin E3 ligase of SREBP1c in HCC cells." (PMID 37828054, 2023). "This study also reveals that PHF2 functions as a tumor suppressor by acting as an E3 ubiquitin ligase of sterol regulatory element-binding protein 1c (SREBP1c), a master transcription factor of lipogenesis." (PMID 37828054, 2023). "The PHF2-WT group showed reduced tumor growth compared to the Vector/ND-fed group, and tumor growth was somewhat increased by PAD feeding (lanes 3-4)." (PMID 37828054, 2023). "Our data demonstrate that PA exerts tumor-proliferating effects on HCC cells by rewiring FA metabolism through the PHF2/SREBP1c axis." (PMID 37828054, 2023). "Nevertheless, the PHF2-WT/PAD-fed group showed much-reduced tumor growth than the Vector/PAD-fed group." (PMID 37828054, 2023). "In the KDM7 family, KDM7A and KDM7B promote the formation of cancer; interestingly, KDM7C/PHF2 inhibits tumor development." (PMID 37218871, 2023). "We next explored the tumor-suppressive role of PHF2 and the dietary effect of PA in the liver microenvironment." (PMID 37828054, 2023). "Overall, these results suggest that palmitoylation-dependent PHF2 degradation enhances both tumor growth and lipid metabolism in tumor-bearing mice." (PMID 37828054, 2023). "The mechanism exploration demonstrated that miR-18b-5p acted as a potential inhibitor of PHF2, a tumor suppressor gene, at post-transcriptional level." (PMID 35729160, 2022). "To identify the ability of miR-18b-5p to promote tumor progression through inhibiting PHF2, we co-transfected MG-63 and 143b cells overexpressing PHF2 or scrambled vector with miR-18b-5p mimic or miR-NC." (PMID 35729160, 2022). "Using the xenograft tumor model in vivo, they found that knockdown of KDM5A and PHF2 not only reduced the tumor burden in the primary tumor but also induced a more pronounced decrease in metastatic disease burden." (PMID 36230825, 2022). "The nuclear expression level of PHF2 and C/EBPα in tumour cells was evaluated, and 187 (54.4%) were classified as low expression and 157 (45.6%) were high expression." (PMID 29416602, 2018). "We demonstrated that a low expression level of PHF2 and C/EBPα was significantly correlated with a larger tumour size, higher WHO/ISUP grade, high pM stage, advanced pTNM stage, and shorter overall, cancer-specific and progression-free survival times." (PMID 29416602, 2018). "The previous studies assessed ADFP and our results suggested that adipogenesis is associated with tumour initiation and decreased adipogenic function of ADFP and PHF2 and C/EBPα with tumour progression." (PMID 29416602, 2018). "PHF2 is known as a histone demethylase and, by doing so, acts as a tumor suppressor." (PMID 37828054, 2023). "The PHF2-C23A group also showed dramatically reduced tumor growth than the Vector/ND group." (PMID 37828054, 2023). "PHD finger protein 2 (PHF2) is a tumor-suppressing histone demethylase." (PMID 34439227, 2021). "Additionally, because PHF2 and C/EBPα are considered to have a tumour suppressive effect, subclones of cancer that suppress PHF2 and C/EBPα would have a survival advantage in tumour progression." (PMID 29416602, 2018). "Moreover, several studies have revealed that PHF2 acts as a tumor suppressor." (PMID 37828054, 2023).
tumor (continued). "Thus, our study not only identifies PHF2-S655 phosphorylation as a biomarker for the prediction of tumor metastasis but also provides the evidence that PHF2 activation maybe a promising strategy for tackling lung cancer metastasis." (PMID 36872368, 2023). "Conversely, the tumor-suppressive role of PHD finger proteins is exemplified by PHF2 and the ING family, which maintain genomic stability and suppress tumor growth through chromatin modification and transcriptional regulation." (PMID 38813086, 2024). "Conversely, it discusses the tumor-suppressive functions of PHD finger proteins, such as PHF2 and members of the ING family, which uphold genomic stability and inhibit tumor growth through their interactions with chromatin and transcriptional regulators." (PMID 38813086, 2024). "Reprogramming is mediated by histone demethylase PHF2 (also called KDM7C) in this model and results in cell differentiation and decreased tumor formation." (PMID 37504297, 2023). "Meanwhile, upregulated miR-221 targets the PHD finger protein 2 (PHF2) gene, a phenomenon that induces its downregulation, as well as tumor dissemination and worrisome survival rates in HCC patients." (PMID 37108330, 2023). "Plant homeodomain finger 2 (PHF2) and CCATT/enhancer binding protein α (C/EBPα) play a role in the epigenetic regulation of adipogenesis, and their tumour suppressive functions have been elucidated." (PMID 29416602, 2018). "In respect to non-tumor control, relative fold reduction in expression of these genes in primary tumors was seen in the following order: FANCC (31.6 ± 36.7) > PHF2 (26.54 ± 44.41) > PTCH1 (19.3 ± 27.8)." (PMID 18990233, 2008). "However, it is also proven to activate some tumor suppressors, including PHD Finger Protein 2 (PHF2) and E-cadherin." (PMID 40721413, 2025). "Because our results showed that PHF2 negatively regulated lipogenesis in HCC cells, we wondered whether PHF2 has a tumor-suppressive role in HCC and what the mediator of PHF2 is." (PMID 37828054, 2023). "To avoid the growth rate difference in vivo, we subcutaneously injected mock, PHF2-WT or S655A mutant A549 cells into balb/c nude mice and no obvious difference of tumor volume or tumor weight was observed." (PMID 36872368, 2023). "The PHF2-C23A group did not exhibit noticeable effect on tumor growth when exposed to PAD feeding (lanes 5–6)." (PMID 37828054, 2023).
cancer (16 papers, 2018 to 2025). A tumor composed of atypical neoplastic, often pleomorphic cells that invade other tissues. "In particular, PHF2 nonsense mutations in exons 12, 16, and 18 have been associated with different cancer types." (PMID 35887017, 2022). "Reprogramming of FA metabolism is a hallmark of cancer cells; therefore, we first examined whether excessive changes in FAs flux could regulate PHF2 levels in HCC cells." (PMID 37828054, 2023). "Immunohistochemical analysis of liver tissues from HCC patients revealed higher ZDHHC23 and SREBP1c expression and lower PHF2 expression in cancer tissues than in adjacent normal tissues." (PMID 37828054, 2023). "FOXP2 was found to directly bind to and activate the promoter of PHF2 that stimulated the epithelial phenotype of cancer cells." (PMID 33718155, 2021). "Our studies thus provide the first evidence for a disease-promotional role for PHF2 in cancer, and highlight the context-dependent action of epigenetic regulators in biology." (PMID 33196691, 2020). "L1CAM, another cell surface protein strongly implicated in cancer progression and metastasis, demonstrated positive regulatory control by KDM5A and PHF2 in both cell lines." (PMID 33196691, 2020). "Higher expression of PHF2 was detected in adjacent cancerous tissues compared to the carcinoma tissues (P< 0.05, paired χ2 test)." (PMID 31214616, 2019). "Multivariate analysis of cancer-specific and progression-free survival with PHF2 and C/EBPα nuclear expression in 344 patients with ccRCC (Cox proportional hazard model)." (PMID 29416602, 2018). "The PHF2 and C/EBPα expression levels had a significant correlation with the overall, cancer-specific and progression-free survival." (PMID 29416602, 2018). "Specifically, the involvement of PHF2 in cancer has been extensively described." (PMID 38890452, 2024). "PHF2 has been less extensively studied in cancer (as recently reviewed)." (PMID 33196691, 2020). "The histone lysine demethylase PHD finger protein 2 (PHF2) is deregulated in various cancers." (PMID 32784607, 2020). "Furthermore, multivariate analysis showed that the combination of PHF2 and C/EBPα expression as an independent prognostic factor for cancer-specific and progression-free survival." (PMID 29416602, 2018). "Multivariate analysis showed that PHF2 expression and C/EBPα expression are independent prognostic factors for cancer-specific and progression-free survival and could act as novel prognostic markers in ccRCC patients." (PMID 29416602, 2018). "Based on the adipogenic role of PHF2 and C/EBPα, we suggested adipogenic metabolic evolution and our consideration may elucidate a therapeutic strategy for cancer cell metabolism." (PMID 29416602, 2018). "Furthermore, multivariate analysis using the Cox proportional hazards model indicated that the PHF2 and C/EBPα expression levels were an independent predictor of cancer-specific and progression-free survival in patients with ccRCC when assessed by the WHO/ISUP grade and pTNM stage." (PMID 29416602, 2018). "Suppression of H3K9me2/me3 demethylase activity such as KDM3A (JMJD1A), KDM4C (JMJD2C), and KDM7C (PHF2) in tissue specific stem cell cultures and cancer cells can lead to premature senescence, increased DNA damage and genomic instability." (PMID 34017357, 2021). "To analyze the levels of selected genes from the grafted human cancer cells, we designed species-specific qPCR primers for FOXP2, E-cadherin, and PHF2 of human and mouse." (PMID 33718155, 2021).
cancer (continued). "We also found PHF2 inhibited HCC cell migration and an evident lower expression of PHF2 was detected in the carcinoma tissues compared with adjacent cancerous tissues." (PMID 31214616, 2019). "PHF2 is located in the human chromosomal region 9q22.32 and is often absent in several cancers, including bladder, esophageal, head and neck, and prostate cancers." (PMID 37828054, 2023).
brain disorder (1 paper, 2026). A disease affecting the brain or part of the brain. "It suggests that targeting PHF2 could be a novel therapeutic approach for AD and other brain disorders involving neuroinflammation." (PMID 40849543, 2026).
PHF2 also shares sentences with these, for which no sentence is quoted: anxiety disorder (2 papers); adrenal Cushing syndrome (1); anorexia nervosa (1); atherosclerosis (1); autism (1); clear cell renal cell carcinoma (1); colorectal cancer (1); depression (1); developmental delay (1); Hyperinsulinemia (1); idiopathic inflammatory myopathy (1); immune diseases (1); laminopathies (1); Lung squamous cell carcinoma (1); metabolic syndrome (1); mood disorder (1); osteosarcoma (1); prostate carcinoma (1); renal carcinoma (1); renal cell carcinoma (1); Splenomegaly (1); Tinnitus (1); type 2 diabetes (1).